TFRC (transferrin receptor)
Diseases named in the same sentence as TFRC in open-access papers (continued):
Sharing a sentence is not in itself a finding about the gene and the disease.
tumor (continued). "Another tumor promoter is the Transferrin receptor (TfR), an important transmembrane glycoprotein involved in iron transport." (PMID 34445382, 2021). "In particular, HFn has been noted to bind human cells by interacting with transferrin receptor 1 (TfR1), which is highly expressed on cancer cells and is commonly used as a targeting marker for tumor diagnosis and therapy." (PMID 35056915, 2021). "B4GALT4, BCL2L1, COPG1, CRB3, GET4, and TFRC showed almost the same expression levels between tumor and normal tissues." (PMID 33850477, 2021). "TFRC is involved in the uptake of the iron-transporting glycoprotein transferrin into cells and helps meet the high demands for iron in tumor cells." (PMID 33690729, 2021). "In summary, three genes (ACACA, SQLE, and PHKG2) in the newly developed signature have established roles in the protection of tumor cells against ferroptosis, whereas TFRC has the opposite effect." (PMID 33989111, 2021). "TFRC expression is known to have an impact on the proliferation, migration and invasion of tumor cells via the JAK/STAT pathway, as well as metastasis." (PMID 34444760, 2021). "Our data also provide new interconnections between tumor-intrinsic iron metabolism and suppressive tumor immune microenvironment through the TF/TFRC axis." (PMID 34389031, 2021). "We found that TFRC is mainly on tumor cells and normal hepatocytes, and Hepa1-6 cells had elevated TFRC levels compared to normal hepatocytes in our mouse HCC model." (PMID 34389031, 2021). "TF and TFRC are two key molecules in transportation of iron ion during ferroptosis, and both genes were low expressed in tumor tissues." (PMID 34906147, 2021). "The transferrin receptor (TfR) is prevalently expressed on rapidly proliferating tumor cells and holds the potential to be the alternative target." (PMID 33854512, 2021). "In fact, tumor cells avidly bind iron and the expression of high levels of transferrin receptor (TfR1) to internalize transferrin-bound circulating iron was observed long ago." (PMID 33804198, 2021). "HCC samples from The Cancer Genome Atlas (TCGA) were enrolled to evaluate the prognostic value of transferrin receptor (TFRC) and its relevance to tumor-infiltrating M2 macrophages." (PMID 34389031, 2021). "Especially, human heavy-chain ferritin (HFn) has shown an intrinsic active tumor targeting ability because it can recognize and bind to human transferrin receptor 1 (TfR1)." (PMID 34821660, 2021). "These novel findings identify tumor TFRC as a valuable target for cancer immunoprevention and immunotherapy." (PMID 34389031, 2021). "The released PTX@TF entered cancer cells via transferrin-receptor-mediated endocytosis and inhibited the survival of tumor cells." (PMID 34959271, 2021). "It has been reported that brain capillary endothelial cells and many malignant tumor cells have overexpression of transferrin receptor (TfR), which is significantly higher than that of other normal cells." (PMID 34820365, 2021). "Targeting of tumor cells is achieved through the abilities of the transferrin receptor 1 (TfR1) and the Scavenger Receptor Class A Member 5 (SCARA5), overexpressed in cancer cells to recognize APO nanocages." (PMID 33572999, 2021). "Exposed BC loop of Human H-chain ferritin (HFn) has a binding site of human transferrin receptor 1 (TfR1) and gives rise to an intrinsic tumor active targeting ability." (PMID 33918853, 2021). "The primary receptor for ferritin is transferrin receptor-1 (TfR1), expressed in many cell lines and tumor tissues." (PMID 34834381, 2021). "One concerns the target CD-71 (transferrin receptor), overexpressed in malignant cells correlated with tumor stage or cancer progression, the object of two clinical trials with CX-2029 and CX-2009 ADCs." (PMID 34206707, 2021).
tumor (continued). "The expression in cancer cells of genes, such as the transferrin receptor (TfR1), ferritin light chain (FTL), and the iron regulatory protein (IRP)-2, is associated with poor prognosis, a higher grade of tumor, and increased resistance to chemotherapy." (PMID 32426284, 2020). "In recent works, we identified that ferritin can target tumor tissues by recognizing transferrin receptor 1 (TfR1) which is highly expressed in tumors 9, 12-15." (PMID 31903145, 2020). "It has been reported that HFn nanocages can bind specifically to tumor cells that overexpress transferrin receptor 1 (TfR1)." (PMID 32610448, 2020). "FLI-FRET in living systems has been extensively validated by our group over the last few years using transferrin–transferrin receptor (Tf-TfR) system in cancer cells, tumor xenografts, and other organs." (PMID 33348564, 2020). "The application of pSi to deliver the anti-cancer drug doxorubicin to transferrin receptor-overexpressing tumour cells across a blood-brain barrier (BBB) model has also been reported." (PMID 32121652, 2020). "Ectopic expression of TFRC partially restored the viability, colony formation ability and xenograft tumor growth of YTHDF1-knockdown cells." (PMID 33204330, 2020). "This DOX nanoformulation exploits the tumor targeting specificity of HFn nanocage, as a result of the specific binding between HFn and the transferrin receptor 1 (TfR1), which is overexpressed in cancers." (PMID 32651443, 2020). "In order to increase iron retention tumor cells express higher levels of iron import proteins, such as transferrin receptor (TFR1) and divalent metal transporter 1 (DMT1)." (PMID 32863212, 2020). "H-ferritin (HFn) nanocarrier is emerging as a promising theranostic platform for tumor diagnosis and therapy, which can specifically target tumor cells via binding transferrin receptor 1 (TfR1)." (PMID 32024821, 2020). "More importantly, we conducted xenograft tumor growth on TFRC knockdown of EJ and T24 BC cell lines." (PMID 30782157, 2019). "Specific receptors that are highly expressed in tumors and on the surface of tumor endothelial cells include transferrin receptor, folate (FA) receptor, integrin receptor, somatostatin receptor, lectin receptor, and epidermal growth factor receptor (EGFR)." (PMID 31915707, 2019). "We took advantage of the natural tumor targeting of H-Ferritin, which is mediated by the transferrin receptor-1 (TfR1)." (PMID 31382388, 2019). "Alternatively, inhibiting transferrin-receptor-dependent iron uptake also results in inhibition of RR and of tumor cell proliferation." (PMID 31191823, 2019). "Uptake of Tf-bound iron is ensured by binding the transferrin receptor (TfR), which was also found to be up-regulated in tumor cells." (PMID 31083487, 2019). "In particular, H-ferritin (HFn) nanocages hold a great promise thanks to their specific tumor homing mediated by Transferrin Receptor-1 (TfR1) internalization." (PMID 31382388, 2019). "More interesting is that cTFRC expression is correlated with TFRC both in tumor cell lines and tumor tissues." (PMID 30782157, 2019). "There is increasing evidence that TFRC is involved in tumorigenesis and tumor progression, and its expression is significantly dysregulated in many cancer types." (PMID 31516392, 2019). "Consistently, TFRC silencing in 3 BC primary tumor cells also impaired cell attachment, migration and invasion." (PMID 30782157, 2019). "The transferrin receptor (TfR) is highly expressed on the surface of rapidly proliferating tumor cells." (PMID 31293575, 2019). "Beyond the leaky BBB, Rutherrin is actively endocytosed via the tumor cell’s transferrin receptor (TfR) enabling uptake by microinvasion distal from the tumor core." (PMID 32642649, 2019). "As the cut‐off size for extravasation has been found to be 400 nm for most tumours, these liposomes have the required sizes to be taken up by the transferrin receptor‐expressing cancer cells." (PMID 31341642, 2019).
tumor (continued). "Tumor cells exhibit increased expression and activity of RR as well as increased expression of the transferrin receptor at the cell surface, enabling enhanced cellular uptake of iron." (PMID 31191823, 2019). "The results showed that TFRC was positively correlated with the tumor grade at mRNA levels, also T stage and tumor lymphatic metastasis." (PMID 30782157, 2019). "In this context, ferritins have been proven particularly useful for the selective targeting to cell populations overexpressing the transferrin receptor (CD71), in particular iron avid tumor cells." (PMID 30102720, 2018). "Ferritin H-homopolymers have been extensively used as nanocarriers for diverse applications in the targeted delivery of drugs and imaging agents, due to their unique ability to bind the transferrin receptor (CD71), highly overexpressed in most tumor cells." (PMID 30102720, 2018). "These two probes allow non-invasive imaging of bombesin and transferrin receptor expression levels on tumor cells as indicators of active energy metabolism." (PMID 28792505, 2017). "More specifically, the finding that human H-ferritin intrinsically targets tumor cells via binding to its receptor transferrin receptor 1 (TfR1) inspired research into using ferritins for tumor target therapy." (PMID 28993977, 2017). "We exploited the natural tumor targeting of H-Ferritin, which is mediated by the transferrin receptor-1 (TfR1), and its physiological tropism toward cell nucleus." (PMID 28790402, 2017). "An important advantage of the HFt system is the ability to be internalized by many types of tumor cells via the transferrin receptor 1 (TfR1)." (PMID 28718812, 2017). "In order to improve the tumor-targeting properties of cisplatin, transferrin (Tf) was employed as a carrier to transfer cisplatin into cancer cells via transferrin receptor 1 (TfR1) mediated endocytosis." (PMID 28484093, 2017). "Due to the high expression of transferrin receptors at the surface of brain capillary endothelial and tumor cells, especially glioma stem cells, targeting the transferrin receptor system provides an avenue for the entry of drug molecules into the brain." (PMID 29088799, 2017). "Microarray profiles in CCA samples (n = 104) showed decreased H ferritin, hepcidin and ferroportin expression in tumours respect to surrounding liver, whereas transferrin receptor was up-regulated." (PMID 29247214, 2017). "It has been reported previously that modulation of iron availability in cancer cells by the use of iron chelating agents or through transferrin receptor-targeted treatments exhibits potent anti-tumor activity, including an anti-HCC effect." (PMID 26657500, 2016). "Compared with normal cells, cancer cells need a lot of iron involved inactive nucleic acid metabolism, while the majority of the surface of the tumor cells has a high density of transferrin receptor (TfR)." (PMID 27739410, 2016). "This study suggests that transferrin-coupled KabC-platelets bind to tumor cells that over-express the transferrin receptor where they are retained through multiple interactions." (PMID 27049725, 2016). "Transferrin receptor (TfR) is overexpressed in many types of tumor cells and therefore is a potential target for the selective delivery of siRNA to cancer cells." (PMID 27735873, 2016). "The expression level of transferrin receptor in tumor, lung, liver and testis were in accordance with the fluorescence intensities in bio-distribution of Cy5.5-Tf-DTPA-Gd in mice." (PMID 27223075, 2016). "The merged image of the tumor slice reveals shows considerable overlap in the distributions of the transferrin receptor (FITC) and test platelets (chlorin e6)." (PMID 27049725, 2016). "We then found that Adpa-Mn achieved its selectivity against cancer cells through the transferrin (Tf)-transferrin receptor (TfR) system, which is highly expressed in tumor cells." (PMID 25604962, 2015).
tumor (continued). "Tumour cells are also known for the upregulation of transferrin receptor expression on the cell surface." (PMID 25435931, 2015). "Previous reports have demonstrated that gambogic acid can inhibit the growth of a wide variety of tumour cell lines, possibly due to its ability to induce apoptosis via the transferrin receptor (TfR1)." (PMID 24623960, 2014). "More importantly, we demonstrated that the anti-TFRC antibody efficiently inhibited OSCC tumor growth in a murine xenograft model." (PMID 24890018, 2014). "In MagA- and HF + LF-expressing tumor cells, we have detected a decrease in transferrin receptor following culture in the presence of iron supplementation." (PMID 24550900, 2014). "The tumor weights were significantly reduced in the anti-TFRC antibody-treated mice compared to the control-treated mice." (PMID 24890018, 2014). "Compared to healthy tissue, tumor cells have reduced levels of ferritin expression and elevated levels of transferrin receptor." (PMID 24550900, 2014). "Because the anti-human TFRC antibody was included among the tumor-specific antigens 13, we determined the function of the anti-human TFRC antibody against several OSCC cell lines." (PMID 24890018, 2014). "Common examples of cell surface targets used for delivery to tumor cells include: transferrin receptor (TfR), folate receptor, and Arginine-Glycine-Aspartic ligands." (PMID 24478715, 2014). "TFRC has an important role in the inflammation process and it has also been described as being specific for tumor cell proliferation as it provides high iron uptake required for cell division." (PMID 24107468, 2013). "Tumor cells generally express higher level of transferrin receptor (TfR) than normal tissues, this led many researchers to utilize TfR as target for immunotherapy." (PMID 24105401, 2013). "Transferrin receptor (TfR) is an endocytic receptor and identified as tumor relative specific due to its overexpression on most tumor cells or tissues, and TfR binds and intakes of transferrin-iron complex." (PMID 23192001, 2012). "These included genes known to be expressed by microglia (CCL8, SPP1, IRF7, IL1RAP), macrophages (IL1RN, SPP1, PDPN, IL1RAP, MDK, TFRC, HRH4), and tumor-associated macrophages (IL6, SPP1)." (PMID 22937035, 2012). "Immunoliposomes have been successfully used in vivo to achieve targeted delivery of tumour-suppressing genes into tumours, using an antibody fragment against the human transferrin receptor." (PMID 22203906, 2011). "Inhibition of TFRC decreases cell proliferation and results in G1 arrest, consistent with the tumor growth inhibition observed in the sensitive cell culture and xenograft experiments." (PMID 20604938, 2010). "Using biochemical methods combined with mass spectroscopy, TfRC, the main iron transporter which binds and internalizes the iron carrier transferrin, was identified as the target for six of these tumor specific mAbs." (PMID 18231595, 2008). "Our data are consistent with the fact that tumor cells express high level of transferrin receptor to meet the increase in iron required by growing tumor tissue." (PMID 17760959, 2007). "Relationship between transferrin receptor (TfR) protein expression and degree of modulation to a combination therapy of artesunate plus iron(II) glycine sulfate in tumor cell lines of the Oncotest panel." (PMID 17726528, 2007). "The novel cationic immunolipoplex incorporating a biosynthetically lipid-tagged, anti-transferrin receptor single-chain antibody (TfRscFv) targeted tumour cells both in vitro and in vivo." (PMID 16792817, 2006). "The cytoreductive effects of anti-transferrin receptor (anti-TfnR) immunotoxins (ITs) and of ricin toxin against tumour micromasses have been evaluated in a multicellular tumour spheroid (MTS) model." (PMID 7669569, 1995). "It has been proposed that Natural Killer (NK) cell activity is involved in host defence against neoplasia, and that NK cells react with or recognize the transferrin receptor (TrR) on target cells." (PMID 2981539, 1985).
tumor (continued). "Notably, tumor iron content remained unchanged in males but was significantly elevated in ID female tumors, complemented by increased transferrin receptor (TfR1) and FTH expression." (PMID 42008565, 2026). "In addition, the expression of transferrin receptor 1 (TfR1) and ferritin in tumor tissue, tumor stroma, and normal lung tissue was analyzed." (PMID 39852175, 2025). "Research has shown that abnormal iron homeostasis in tumor cells is manifested mainly by increased expression of ferritin, transferrin, transferrin receptor, and hepcidin, leading to increased iron absorption and storage and ultimately causing iron overload in tumor cells." (PMID 41551149, 2025). "Additionally, acidic conditions promote iron release, and tumor cells upregulate transferrin receptor 1 (TfR1) to meet proliferative demands." (PMID 40755757, 2025). "It is worth noting that in the previous analysis of the expression of TATs in normal and tumor tissues of four common gynecological tumors, we found that CD71 (also known as transferrin receptor) is a target overexpressed on the surface of gynecological malignant tumor cells." (PMID 40046734, 2025). "Thus, nucleotide metabolism is not only a metabolic hallmark of CRC but acts as a central focal point that coordinates tumor-stromal-immune signaling (via MIF/PLA2/BAFF/TFRC) and spatially co-localizes with oncogenic pathways." (PMID 41450739, 2025). "As a result, TFRC is activated, facilitating tumour cells to absorb iron bound to transferrin." (PMID 41153383, 2025). "The T7 peptide (HAIYPRH) is a transferrin receptor (TfR)-binding peptide that has a strong affinity for TfRs (the expression level on tumor cells is about seven times that of healthy cells), and this binding force is very similar to transferrin, but they have different binding sites." (PMID 39339228, 2024). "Similar results were observed in the tumour tissues of mice treated with anlotinib alone or in combination with anti‐PD‐1 (all p‐values < 0.05), indicating that anlotinib inhibits TFRC through inactivation of the VEGFR2/AKT/HIF‐1α axis." (PMID 39095323, 2024). "Further studies reveal that tumor cell uptake is FH density‐dependent through active binding with transferrin receptor 1, whereas in vivo tumor accumulation and tissue penetration are found to be correlated to heterogeneous assembly of FHn and vascular permeability of tumors." (PMID 38368258, 2024). "CD8+ T‐cell infiltration into the tumour microenvironment correlated with low expression of TFRC." (PMID 39095323, 2024). "The RAB17-induced tumor growth was significantly inhibited by TFRC expression." (PMID 39242574, 2024). "Interestingly, LASS2 overexpression reversed the changes in TFRC levels induced by either Fer-1 or erastin in these tumour cell lines." (PMID 38419028, 2024). "TFRC was identified as a prognostic biomarker and could promote tumor progression in multiple cancers." (PMID 39582531, 2024). "RT-qPCR results determined that TFRC was generally downregulated in LC tumor tissues." (PMID 38221933, 2024). "In addition, IGF2BP2 can bind to TFRC to regulate iron metabolism and enhance tumor growth and proliferation." (PMID 37088822, 2023). "Notably, human Ftn possesses high affinity to transferrin receptor 1 (TfR1), a receptor overexpressed in many tumor cells." (PMID 37849678, 2023). "We also quantified the expressions of a ferroptosis marker gene PTGS2 and NRF2 downstream genes HMOX1 and TFRC in tumor tissues and found their expressions were all elevated by IKE treatment in mice received a control diet, but not in mice receiving methionine-free diet." (PMID 37553341, 2023). "HFn nanocages exploited the natural tumour targeting mediated by transferrin receptor-1 (TfR1)." (PMID 37048731, 2023). "Importantly, tumoral c-Jun expression was positively correlated with SOX9, SOX2, OCT4, FTH1, FTL and TFRC expression in consecutive PDAC tumour tissues." (PMID 37143164, 2023).